IL6 (interleukin 6)
Diseases named in the same sentence as IL6 in open-access papers (continued):
Sharing a sentence is not in itself a finding about the gene and the disease.
chronic thromboembolic pulmonary hypertension (2 papers, 2021 to 2024). Chronic thromboembolic pulmonary hypertension (CTEPH) is characterized by the persistence of thromboemboli in the form of organized tissue obstructing the pulmonary arteries. "Also, in patients with chronic thromboembolic pulmonary hypertension (CTEPH), different cytokines showed increased levels, such as IL-1β, IL-2, IL-4, IL-6, IL-8 and IL-10." (PMID 38612795, 2024). "Moreover, increased levels of IL-6 following VTE are associated with an increased risk of VTE-related complications, in particular post-thrombotic syndrome (PTS), chronic thromboembolic pulmonary hypertension (CTEPH), and infections." (PMID 33807848, 2021).
CINCA syndrome (2 papers, 2021 to 2022). Chronic Infantile Neurological, Cutaneous, and Articular (CINCA) syndrome is characterized by skin rash, joint involvement, chronic meningitis with granulocytes and, in some cases, sensorineural hearing loss and ocular signs. "Importance: Multisystem Inflammatory Syndrome in Children (MIS-C) associated with SARS-CoV-2 infection is thought to be driven by a post-viral dysregulated immune response, where interleukin 6 (IL-6) might have a central role." (PMID 34869111, 2021).
clonorchiasis (2 papers, 2015 to 2020). Infection of the biliary passages with clonorchis sinensis, also called Opisthorchis sinensis. "In our previous study, we showed dramatic changes of TLR2 and TLR4, and production of IFN-γ, IL-6, TNF-α, and IL-10 in the spleen were regulated by TLR4 as demonstrated in a murine model of clonorchiasis using TLR4 defective mice." (PMID 33489026, 2020).
Cn (2 papers, 2024 to 2025). "Our findings provide insight into the dynamic role of IL-6 in neurocryptococcosis and offer novel research avenues in the study of Cn pathogenesis." (PMID 39334365, 2024). "In conclusion, we have demonstrated that IL-6 has a significant role in combating Cn systemic infection in mice." (PMID 39334365, 2024). "Similarly, elevated IL-6 and TNF-α levels were reported in a case of cyclic neutropenia associated with RB." (PMID 41250711, 2025). "We investigated the importance of IL-6 in systemic Cn disease using colony forming units (CFU) determinations and histopathological examinations of lung and brain tissue removed from Cn-infected-Wild-type, -IL-6−/−, and -IL-6−/− + rIL-6 mice at 3- and 7-dpi." (PMID 39334365, 2024).
CNS demyelinating diseases (2 papers, 2013 to 2021). "We measured the CSF concentration of each cytokine in 20 AE patients, and compared IL-6 and IL-17A concentrations with 13 patients with CNS demyelinating diseases and 20 non-inflammatory controls." (PMID 34054854, 2021).
collagenous colitis (2 papers, 2013 to 2014). A type of microscopic colitis of unknown etiology. "There was significantly increased production of the proinflammatory cytokines IFN-γ, IL-17A, IL-6, and IL-1β in the presence of CM generated by culture of denuded biopsies (DNB-CM) from the colon of collagenous colitis patients, compared to DNB-CM from noninflamed controls." (PMID 25332518, 2014).
COPA syndrome (2 papers, 2022 to 2023). "COPA syndrome is associated with autoantibody development, increased Th17 cells and pro-inflammatory cytokine expression including IL-1β and IL-6." (PMID 37317175, 2023).
cutaneous lupus erythematosus (2 papers, 2020 to 2024). An autoimmune disorder that manifests as different lupus-specific skin disorders; it can occur with systemic lupus erythematosus, or as a singular disease. "Several pro-inflammatory cytokines, such as TNF, IL-12, and IL-6, show increased levels in skin lesions of patients with cutaneous lupus erythematosus (CLE) compared to non-lesional skin or skin of healthy individuals." (PMID 39618670, 2024).
Cystic tumors (2 papers, 2024). "High levels of inflammatory mediators (e.g., IL6, IL8, IL1) have been observed in ACP in both the cystic and solid components, and targeting with the IL6 inhibitor Tocilizumab has shown modest responses in cystic tumours and is under evaluation in clinical trials (NCT05233397)." (PMID 39127699, 2024). "Cystic tumors exhibited higher expression of IL1B, IL6, IL10, and TNF (all P < 0.05) than non-cystic tumors." (PMID 38965454, 2024).
cystoid macular edema (2 papers, 2011 to 2021). An autosomal dominantly inherited cystoid macular edema manifesting with macular atrophy, strabismus and, sometimes, pericentral retinitis pigmentosa. "Higher levels of IL-6 and IL-8 were found in IU patients with cystoid macular edema (CME) compared to non-CME IU patients (p=0.026 and 0.012, respectively)." (PMID 21850175, 2011).
diabetic eye disease (2 papers, 2024 to 2026). A group of disorders affecting the eye in patients with diabetes mellitus. "Inflammation is increasingly recognized as a pivotal pathogenic driver in diabetic eye disease, with Interleukin-6 (IL-6) identified as a central mediator of acute and chronic inflammatory responses." (PMID 42079665, 2026). "The secretion of VEGF and IL-6 plays a critical role in diabetic eye diseases." (PMID 38438663, 2024).
DRESS syndrome (2 papers, 2015 to 2024). "Our DRESS syndrome case e.g. with multivalent drug hypersensitivity had highly elevated IL-6 release with the relevant culprit drug at 0.15 μM, whereas another non-culprit drug (by history) has caused the peak exclusively at 0.5 μM." (PMID 25709746, 2015).
dysphoria (2 papers, 2021 to 2022). Dysphoria is a profound state of unease or dissatisfaction. "While IL-6 was a modest confounder (14.5% change in the beta coefficient), the relationship remained significant after adjusting for IL-6, age, gender, years of education, multimorbidity, and dysphoria." (PMID 35742625, 2022).
dysthymia (2 papers, 2017 to 2024). "Increased IL-6 concentrations in CSF were significantly correlated with dysthymia, supporting the role of central cytokines in dysthymia with broad implications for the pathophysiology of depression in patients." (PMID 29225332, 2017).
dystrophin deficiency (2 papers, 2015 to 2017). "Observations of reduced circulating levels of IL-6 and pro-inflammatory Ly6Chigh monocytes in ApoE/mdx mice also suggested a general dampening of inflammatory activation as a result of dystrophin deficiency." (PMID 26345322, 2015). "Some of these studies showed that the functional blockade of NF-κB or the inflammatory cytokines, such as TNF-α, IL-6 and IL-1β are a specific therapeutic strategy for the treatment of dystrophinopathies." (PMID 28787441, 2017).
Ehrlich tumor (2 papers, 2022 to 2024). "Our results indicated that treatment of ascitic Ehrlich tumors with CE led to increased IL-6 levels in the ascitic fluid of induced animals." (PMID 39861087, 2024). "Consistent with those, our data showed excessive activation of STAT3, demonstrated by STAT3 phosphorylation, in response to elevated IL-6 plasma concentration in Ehrlich tumor-bearing mice compared to controls." (PMID 35847939, 2022). "However, some studies indicate that IL-6 levels tend to be increased after 14 days of induction of ascitic Ehrlich tumors and be reduced in the same period after treatment with Bothrops jararaca venom and indomethacin." (PMID 39861087, 2024). "Our results indicate that treatments with CE and EAF, both at a 10% concentration, were able to regulate the metabolic imbalance caused by the tumor and inhibit the growth of ascitic and solid Ehrlich tumors by inducing apoptosis and modulating mast cells and the cytokines IL-6 and TNF-α." (PMID 39861087, 2024). "In agreement with previous studies using different cancer cachexia models, Ehrlich tumor development presented characteristics of pro-inflammatory scenario, as demonstrated by significant (P <.05) elevated TNF-α and IL-6 in plasma of tumor-bearing mice compared to the control group." (PMID 35847939, 2022).
endometrial adenocarcinoma (2 papers, 2024 to 2025). "Similarly, in a study investigating the role of the pro-inflammatory cytokine interleukin-6 (IL-6) on human endometrial adenocarcinoma MFE-296 cells, IL-6 increased the generation of ROS by enhancing NADH oxidase levels and inducing the cellular release of mtDNA." (PMID 38993645, 2024).
Endometrial Cyst (2 papers, 2022 to 2024). It is caused by endometriosis, and formed when a tiny patch of endometrial tissue (the mucous membrane that makes up the inner layer of the uterine wall) bleeds, sloughs off, becomes transplanted, and grows and enlarges inside the ovaries. "Importantly, IL-6 mediates numerous inflammatory signals of both innate and adaptive systems, taking part in establishing the systemic and local inflammation associated with endometrial cysts." (PMID 38732021, 2024). "Analysis of blood serum in patients with endometrial cysts revealed significantly elevated levels of interleukin-6 (IL-6) in both blood serum as well as in the endometrioma and its surrounding tissues." (PMID 38732021, 2024).
endometrial tumors (2 papers, 2019 to 2024). "Therefore, the elevated production of IL-6 and IL-1β in the endometrial tumors might participate to local inflammation as well as cytotoxic effector inhibition and disease progression." (PMID 31105699, 2019). "All together, we showed that both cytokine and chemokine production in the endometrial tumors may participate to the alteration of NK cell function, as IL-6 and IL-1β are increased in the tumor, and recruitment, as chemoattractants CCL27, CXCL12, and CCL21 are significantly reduced in the tumor." (PMID 31105699, 2019).
eosinophilic granulomatosis with polyangiitis (2 papers, 2014 to 2025). Eosinophilic granulomatosis with polyangiitis (EGPA), previously known as Churg-Strauss syndrome, is a systemic vasculitis of small-to medium vessels, characterized by asthma, transient pulmonary infiltrates, and hypereosinophilia. "Therapies targeting interleukins such as IL-6 (e.g., tocilizumab) and IL-5 (e.g., mepolizumab) have been explored, particularly in eosinophilic granulomatosis with polyangiitis (EGPA), a subset of AAV." (PMID 40507398, 2025).
Erythema nodosum (2 papers, 2022 to 2024). An erythematous eruption commonly associated with drug reactions or infection and characterized by inflammatory nodules that are usually tender, multiple, and bilateral. "We confirmed that ocular BS was more prevalent in male patients and more likely to have erythema nodosum and vascular involvement, while intestinal BS tends to have fever and hematologic involvement accompanied with elevated inflammation markers including ESR, CRP, SAA, and IL-6." (PMID 35488313, 2022).
eye inflammation (2 papers, 2022 to 2025). "MSC-Exos–sourced miR-204 modulated IL-6/IL-6R/Stat3 pathway in eye-infiltrated macrophages, suppressed IL-6-driven eye inflammation, and attenuated DED-related symptoms in experimental animals." (PMID 39839752, 2025).
fallopian tube cancer (2 papers, 2013 to 2021). A primary or metastatic malignant neoplasm that affects the fallopian tube.
familial pulmonary arterial hypertension (2 papers, 2019 to 2021). "It has been proposed that the onset of familial pulmonary arterial hypertension involves a two-hit event comprising a BMP receptor loss of function mutation and dysregulation of IL6." (PMID 34660588, 2021).
fasciolosis (2 papers, 2017 to 2026). "The role of IL‐6 in fasciolosis remains incompletely understood, as it has been implicated in both promoting host immune responses and contributing to parasite persistence." (PMID 41503693, 2026).
fertility disorders (2 papers, 2008 to 2009). "However, our data showed that highest IL-6 levels were produced in inc-stimulated cells from CT-positive patients with fertility disorders suggesting the pathogenic role of IL-6." (PMID 19397832, 2009). "In contrast, IL-1β, IL-4, IL-5, IL-6 and IL-10 mRNA expression levels were significantly higher (P < 0.05) in cells obtained from CT-positive women with fertility disorders compared to other two groups." (PMID 19397832, 2009). "In contrast, IL-1 Beta, IL-4, IL-5, IL-6 and IL-10 levels were found to be higher in CT-positive women with fertility disorders compared to CT-positive fertile women and controls (P < 0.05)." (PMID 19397832, 2009). "Significantly higher levels of IL-1β, IL-6 and IL-10 were detected upon inc-stimulation of cervical cells and PBMCs from CT-positive women with fertility disorders as compared to CT-positive fertile women or controls (P < 0.05)." (PMID 19397832, 2009). "When cervical washes were studied for cytokine concentrations it was seen that in Chlamydia positive women with fertility disorders significantly higher levels of IL-6, IL-8, IL-10 and IFN-γ were present compared to the other groups." (PMID 18828896, 2008). "Number of pDCs/cervical sample in women with fertility disorders showed significantly high correlation with IL-6 levels (r = 0.78; P < 0.01) and IFN-γ levels (r = 0.58; P < 0.05)." (PMID 18828896, 2008). "Significantly higher levels of IL-6, IL-8, Il-10 and IFN-γ (P < 0.05) were observed in Chlamydia positive women with fertility disorders compared to Chlamydia positive fertile women and controls." (PMID 18828896, 2008). "β-estradiol levels were significantly higher in women having fertility disorders as compared to fertile women and have significant correlations (r = 0.65; P < 0.05) with pDCs numbers, CD80 expression, IL-6 levels and IFN-gamma levels in these women." (PMID 18828896, 2008). "pDCs correlated significantly with C-reactive protein levels, IL-6 and IFN-gamma levels in women with fertility disorders." (PMID 18828896, 2008). "IL-6 and IFN-γ levels also showed significant correlation with estradiol levels in women with fertility disorders (r = 0.49 and 0.73 respectively)." (PMID 18828896, 2008). "We detected significantly high levels of estradiol in women with fertility disorders, which correlated significantly with pDC levels, CD80 expression and IL-6 and IFN-γ secretion." (PMID 18828896, 2008). "Both incs induced high levels of IL-6 in cells from CT-positive fertile women with or without fertility disorders in comparison to controls." (PMID 19397832, 2009).
filariasis (2 papers, 2012 to 2022). "The same trend was observed in the case of P. falciparum single infection (for IL-6 only) for filariasis and intestinal protozoal infection (for all)." (PMID 35421083, 2022). "infection when co-infected with filariasis, according to the association with a higher IL-10/TNF-α ratio, and when co-infected with intestinal parasites, according to the association with a higher IL-10/IL-6 ratio." (PMID 35421083, 2022).
fluorosis (2 papers, 2022 to 2024). "Therefore, the present study aimed to further investigate the role of the CXCL12/CXCR4 signaling axis and the related inflammatory factors IL-1β, TNF-α, IL-6 and NF-κB in the mechanism of fluorosis-induced liver injury at the cellular level." (PMID 38905184, 2024). "Although inflammatory damage is not widely recognized as a major component of fluorosis, fluorosis has been shown to cause increased expression of inflammatory factors such as IL-6." (PMID 38905184, 2024). "Researchers found that genes related to signal transduction (G-protein, ERK, MEK1, and MEK2), immune lymphokines (interleukin 6, interleukin 8), and estrogen receptors may influence the occurrence and development of fluorosis." (PMID 36583212, 2022). "Whether inflammatory factors such as SDF-1/CXCR4, IL-6, TNF-α, NF-κB, and IL-1β play a role in the hepatic system due to fluorosis deserves further exploration." (PMID 38905184, 2024).
folate (2 papers, 2021 to 2023). "In contrast, folate deficiency significantly increased pro-inflammatory cytokine IL-6 and TNF-α secretions which were not significantly affected by HFF." (PMID 37630806, 2023). "Additionally, protein–energy malnutrition may induce a high level of systemic inflammatory factors, such as tumor necrosis factor (TNF)-α and interleukin-6, can facilitate tumor cell proliferation invasion and metastasis, and can enhance malignant properties." (PMID 34765561, 2021).
follicular lymphoma (2 papers, 2018 to 2023). Follicular lymphoma is a form of non-Hodgkin lymphoma characterized by a proliferation of B cells whose nodular structure of follicular architecture is preserved. "When considering NHL subtypes (available online), we find that levels of circulating IL-6 had a modest association with DLBCL, and pairwise comparisons of follicular lymphoma versus DLBCL showed a modest difference." (PMID 30873511, 2018).
fragile X syndrome (2 papers, 2025). A genetic syndrome caused by mutations in the FMR1 gene which is responsible for the expression of the fragile X mental retardation 1 protein. "In Fragile X syndrome (FXS) models, aberrant synapse formation and increased excitatory synapses are associated with elevated IL-6, emphasizing its role in excitatory/inhibitory imbalance." (PMID 41292555, 2025).
frontal lobe epilepsy (2 papers, 2023 to 2024). A localization-related (focal) form of epilepsy characterized by seizures which arise in the frontal lobe. "Serum samples collected from patients with videoEEG-verified temporal or frontal lobe epilepsy (TLE or FLE) or TLE + PNES showed increased interleukin-6 (IL-6) levels in between seizures (interictally), compared to controls." (PMID 36895367, 2023). "Interictal levels of interleukin-6 (IL-6) were increased in serum samples from patients with video-EEG-verified temporal or frontal lobe epilepsy (TLE or FLE, respectively) or TLE + PNESs as compared to healthy controls, while patients with PNESs did not demonstrate an increase in IL-6." (PMID 39000494, 2024).
fungal meningitis (2 papers, 2023 to 2025). Meningitis caused by fungal agents which may occur as opportunistic infections or arise in immunocompetent hosts. "Furthermore, cryptococcal researchers have demonstrated that without IL-6, there is increased permeability of the BBB during fungal meningitis, indicating that this C. neoformans-induced IL-6 is integral to preventing fungal migration from the periphery to the CNS." (PMID 40985448, 2025).
fungal pulmonary infection (2 papers, 2023 to 2025). "More patients received IL-6 antagonist treatment in this study acquired bacterial or fungal pulmonary infection, the infected patients had high mortality." (PMID 37901822, 2023).
Gastric Metaplasia (2 papers, 2013 to 2020). Intestinal metaplasia of the gastric mucosa is an intermediate precancerous gastric lesion in the gastric cancer cascade from chronic gastritis and atrophy to dysplasia and adenocarcinoma. "While in vitro experiments showed that IL-6 trans-signalling can overcome the repressive effects of trefoil factor 1 (TFF1) on IL-6 classic-signalling, gastric metaplasia induced by a hyperactive gp130 variant was not abrogated by a dimerised form of soluble gp130 (sgp130Fc)." (PMID 32698506, 2020). "Given that IL-1β induces gastric metaplasia and stimulates expression of the proto-oncogene IL-6 in various cell types, we hypothesized that IL-1β induces expansion of the SPEM phenotype by stimulating proliferation and IL-6 expression along with phosphorylation of STAT-3 (pSTAT-3)." (PMID 23520544, 2013).
gastrointestinal stromal tumor (2 papers, 2015 to 2021). "Administration of imatinib after agonistic anti-CD40 antibody activated TAMs, redirected TAMs to antitumor M1 phenotype, by increased TNF and IL-6 production through the NFκB pathway along with decreased IL-10 production in mouse model of gastrointestinal stromal tumor GIST." (PMID 34209679, 2021).
generalized seizures (2 papers, 2020 to 2021). "IL-6, a key inflammatory molecule, plays a pivotal role in the progress of the excitatory mechanism of the brain and is well-connected with the development of generalized seizures." (PMID 34354662, 2021).